IL17A (interleukin 17A)
Diseases named in the same sentence as IL17A in open-access papers (continued):
Sharing a sentence is not in itself a finding about the gene and the disease.
escherichia coli infection (36 papers, 2014 to 2026). Infection with the organism Escherichia Coli. "Additionally, baicalin reversed the decrease in the proportion of IL-17A+ cells and the Th17/Treg ratio caused by E. coli infection." (PMID 39707535, 2024). "Since a high level of IL-17A was detected in mouse brains after E. coli infection, we next investigated the function of IL-17A in regulating BBB permeability." (PMID 35221923, 2022). "Interleukin-17A (IL-17A) is recognized as a pro-inflammatory cytokine that is released during meningitic E. coli infection." (PMID 35221923, 2022). "Another major issue concerns the characterization of the cells that overexpress the genes for IL-17A and IL-17F upon E. coli infection." (PMID 26062913, 2015). "The authors of this study discovered that interleukin-17A might help mammary epithelial cells to become more effective in fighting off germs after contracting an E. coli infection." (PMID 36134995, 2022). "We can speculate that different cell types secrete IL-17A and IL-22 during an E. coli infection or LPS inflammation episode because IL-17A/F and IL-22 concentration increases in milk did not coincide." (PMID 33059767, 2020). "It is therefore possible that IL-17A levels could be detected in milk at later time points in the case of E. coli infections, explaining our failure to measure IL-17A in milk from E. coli infected cows 24 hours post-infection." (PMID 26062913, 2015). "We therefore chose to investigate in more details if IL-17A could increase the response of the host to E. coli infection by modulating the pro-inflammatory response of MEC." (PMID 26062913, 2015). "Considering that IL-17A has generally more potent effects than IL-17F on epithelial cells, we then explored if IL-17A in particular could contribute to the defence of the host against E. coli infection by modulating the innate immune response of MEC." (PMID 26062913, 2015). "Subsequent flow cytometry analysis showed that E. coli infection increased the numbers of CD3+ and Foxp3+ cells, decreased IL-17A+ cells, and reduced Th17/Treg ratios." (PMID 39707535, 2024). "We demonstrate that IL-17A mediates TJs and AJs breakdown, thereby augmenting BBB permeability via inhibiting PRTN3/PAR2 axis during meningitic E. coli infection, leading to severe neuroinflammation and neuronal injury." (PMID 35221923, 2022). "Most interestingly, we were able to demonstrate that a potential role for IL-17A is to increase the pro-inflammatory and antimicrobial responses of MEC after E. coli infection." (PMID 26062913, 2015). "The beneficial roles of IL-17A have been demonstrated in mice in the context of BCG vaccination, pneumococcal infection in humans, Mycoplasma hyopneumoniae infection in swine, and enterotoxigenic E. coli infection and oral immunization with F4 fimbriae in swine." (PMID 36369044, 2022).
respiratory infection (36 papers, 2010 to 2025). "By further exploring the role of inflammatory IL-17A signaling in MH infections, we hope to expand therapeutic intervention strategies for severe respiratory infections that contribute to the pathogenesis of BRDC." (PMID 34869750, 2021). "Taken together, these data show that the microbiota promotes GM-CSF production during respiratory infection through IL-17A signaling." (PMID 29142211, 2017). "The evaluation of γδ T-cells in COPD has been difficult as this mucosal T-cell population is relatively rare; however, it is known that in response to respiratory infection such as Streptococcus pneumoniae, γδ T-cells can become a major source of IL-17A." (PMID 26201093, 2015). "We first chose to focus our efforts on cytokines known to be essential for survival of primary murine LVS respiratory infection: IL-17A, IFN-γ, and TNF." (PMID 26379269, 2015). "Data from numerous cytokine profiles suggest that the recurrent respiratory infections suffered by our GS patient could be related to the intracellular expressions of IL-17A and IFN-γ." (PMID 29850635, 2018). "To investigate this, first we analyzed lung IL-17A levels during respiratory infection." (PMID 29142211, 2017). "Furthermore, PLY promotes the secretion of cytokines including IFN-γ and IL-17A by splenocytes and is essential for S. pneumoniae to promote the production of IFN-γ by NK cells and IL-17A by γδ T cells in the lung following respiratory infection." (PMID 21085613, 2010). "Several preclinical and clinical studies of bronchoalveolar lavage (BAL) samples from patients with other respiratory infections and diseases have identified tissue-resident immune cells that may produce IL-17A and IFN-γ, although the specific role of these cytokines is not clear." (PMID 32958614, 2020). "The persistence of IL-17A+ cells within the airway mucosa of people with chronic lung disease may not only sustain inflammation, but may also alter essential host defence to respiratory infections, leading to excessive inflammatory responses during exacerbations." (PMID 26201093, 2015). "A cytokine profile of GS patients is not available, however, it was suggested that recurrent respiratory infections suffered by these patients could be related to the intracellular expressions of IL-17A and IFN-γ." (PMID 36059463, 2022). "Moreover, targeting IL-17A when chronic infection is already established limits immunopathology, without compromising resistance to P. aeruginosa respiratory infection." (PMID 27189736, 2016).
toxoplasmosis (36 papers, 2009 to 2025). A parasitic disease contracted by the ingestion or fetal transmission of toxoplasma gondii. "In the case of recurrent abortion women with toxoplasmosis, the genotype AA and allele A of IL‐17A have been identified as protective factors." (PMID 38270309, 2024). "The SNP of IL‐17A has been found to have different associations with recurrent abortion women infected with toxoplasmosis." (PMID 38270309, 2024). "A study found that the NOD2 rs3135499 polymorphism is associated with enhanced production of IL‐17A in human toxoplasmosis." (PMID 30950247, 2019). "On the other hand, in recurrent abortion women (without toxoplasmosis), the allele G of IL‐17A has been identified as a risk factor, but we not found any study in non‐ pregnant population." (PMID 38270309, 2024). "Allele frequencies of IL‐17A, IL‐17F, and IL‐6 polymorphisms in HIV patient with and without toxoplasmosis." (PMID 38270309, 2024). "Genotype analysis of IL‐17A, IL‐17F, and IL‐6 serum level in HIV patient with and without toxoplasmosis." (PMID 38270309, 2024). "Regression analysis of IL‐17A, IL‐17F, and IL‐6 SNP genotypes in HIV patients with and without toxoplasmosis." (PMID 38270309, 2024).
alcoholic liver diseases (34 papers, 2010 to 2026). A disorder caused by damage to the liver parenchyma due to alcohol consumption. "Research has revealed that transplantation of healthy intestinal microbiota can facilitate the expression of IL-17A dependent on microorganisms, which is conducive to restoring the intestinal barrier in alcoholic liver disease." (PMID 40019272, 2025). "In different types of chronic liver diseases, such as autoimmune hepatitis (AIH) or alcoholic liver disease, the frequency of IL-17A–producing cells and the expression of Th17-related cytokines were also significantly elevated." (PMID 36625344, 2023). "Patients with alcoholic liver disease have dramatically elevated serum IL-17A level, which mobilized neutrophil and led to acute alcohol liver disease through acting on hepatic stellate cells to trigger IL-8 and GRO-α production." (PMID 24069246, 2013).
autoimmune uveitis (34 papers, 2009 to 2025). An autoimmune form of uveitis (disease). "IL‐17A, secreted by Th17 cells that are important for the development of autoimmune uveitis, was also elevated in the retina and ciliary body in EAU mice." (PMID 40156826, 2025). "In the retina, IL-17A is known to be involved in the pathogenesis of autoimmune uveitis, AMD and DR." (PMID 34356895, 2021). "Studies in human blood cells have demonstrated that cytokines associated with the adaptive immune system such as IL-17A and IFN-γ play key roles in the pathogenesis of autoimmune uveitis." (PMID 31795515, 2019). "Recent papers reported that IL-33 attenuates EAE and experimental autoimmune uveitis by suppressing IL-17A and IFN-γ production." (PMID 26161006, 2015). "In addition, IFN-γ and IL-17A of specific T cells in mice with autoimmune uveitis have cytotoxic effects on photoreceptor cell proliferation." (PMID 36311731, 2022). "A previous study reported that an IL-17A negative feedback loop limited Th17 pathogenicity in experimental autoimmune uveitis (EAU)." (PMID 38007487, 2023). "Humanized anti-IL-17A antibody has been evaluated in the setting of non-infectious autoimmune uveitis showing clinical benefits when delivered intravenously at 10–30 mg/kg biweekly for two months." (PMID 31795515, 2019). "A study of autoimmune uveitis and its animal model (EAU) demonstrated that blocking IL-17A alone in autopathogenic Th17 cells did not reduce their pathogenicity, but increased the expression of GM-CSF and IL-17F." (PMID 40621455, 2025).
epilepsy (34 papers, 2015 to 2025). A brain disorder characterized by episodes of abnormally increased neuronal discharge resulting in transient episodes of sensory or motor neurological dysfunction, or psychic dysfunction. "In summary, we showed that IL-17A deletion could alleviate epilepsy-associated anxiety disorder, possibly by reducing hilar EGC production and excitotoxic neuronal death." (PMID 35875667, 2022). "More rigorous research is necessary to conclude the accurate role of IL-17A in hippocampal neuronal excitability in epilepsy." (PMID 35875667, 2022). "The level of IL-17A is also reported to be higher in patients with generalized anxiety disorder, suggesting a potential role of IL-17 in epilepsy and anxiety disorder." (PMID 35875667, 2022). "Th17 cells have been demonstrated to be involved in inflammatory responses in many autoimmune diseases that impact the nervous system, highlighting the key role for Th17/IL-17A signaling in the pathogenesis of seizure disorders." (PMID 27882059, 2016). "Recently, it was reported that the level of IL-17A, either in the cerebrospinal fluid (CSF) or in the peripheral blood of patients with epilepsy, was significantly elevated and the level of IL-17A was highly correlated with seizure frequency and severity." (PMID 27882059, 2016). "Among 14 cytokines, four independent biomarkers (IL-6, IFNγ, IL-17a and IFNλ3) for severe seizures in three different types of epilepsy were identified." (PMID 26626560, 2015). "Multivariate regression analysis indicated that interictal concentrations of serum IL-6, IFNγ, IL-17a, IFNλ3, and CSF IL-6, IL-17a, IFNλ3 were significant biomarkers for patients with severe epilepsy." (PMID 26626560, 2015). "If VA score was applied, IL-1Ra, IL-6, IFNγ, IFNλ3 and IL-17a were severity markers in all types of epilepsy." (PMID 26626560, 2015). "If seizure frequency was used for seizure severity, then levels of IL-6, IL-8 and IL-17a were significant biomarkers in all three types of epilepsy." (PMID 26626560, 2015). "Clinical studies have found that IL-17A concentrations in serum and cerebrospinal fluid are positively correlated with seizure frequency and the occurrence of status epilepticus in both pediatric and adult epilepsy patients." (PMID 41306289, 2025). "Pro-inflammatory CD4+ T cells could also cause neuronal damage in vivo and directly lead to intractable seizure in an animal model of epilepsy partly through secreting interleukin-17A and granulocyte-macrophage colony-stimulating factor." (PMID 36330432, 2022). "Taken together, these findings raise the possibility that IL-17A in epilepsy may contribute to anxiety disorder via the regulation of hippocampal neurogenesis." (PMID 35875667, 2022). "Interictal serum IL-6, IFNγ, IL-17a, IFNλ3, and CSF IL-6, IL-17a, IFNλ3 could be used as potential biomarkers for severe epilepsy." (PMID 26626560, 2015). "mRNA levels of IL-6, IFNγ, IL-17a, and IFNλ3 were elevated in different types of epilepsy." (PMID 26626560, 2015). "Elevated concentrations of interleukin-6 (IL-6), interferon-gamma (IFN-γ), and interleukin-17A (IL-17A) have been observed in the plasma during the interictal phase of epilepsy, whereas IL-1β, TNF-α, and IL-10 did not rise in comparison to a healthy group." (PMID 39861097, 2024). "Neither epilepsy-related differences nor brain region × epilepsy interactions were detected for brain IL-17A levels." (PMID 27737716, 2016). "However, epilepsy in patients with NIND does not result in a high level of CSF IL-17A or IL-6 as compared to immune-mediated epilepsy in the elderly." (PMID 34054854, 2021). "Finally, Wang, Wang found that in three distinct types of epilepsy, namely temporal lobe epilepsy (TLE), extra-temporal lobe epilepsy (XLE), and idiopathic generalized epilepsy (IGE), only four independent cytokine biomarkers (IL-6, IFN-γ, IL-17-a, and IFN-λ3) are correlated with severe seizures." (PMID 39861097, 2024).
gastritis (34 papers, 2008 to 2026). Inflammation of the stomach. "Third, within gastric mucosa from H. pylori-infected patients, higher IL-17A protein levels were closely associated with more severe gastritis." (PMID 39022746, 2024). "Th17 cells and their key cytokine, IL-17A, are implicated in the pathogenesis of gastritis induced by H. pylori, while animal studies have shown that EBV directly induces the secretion of the proinflammatory cytokine IL17." (PMID 35053587, 2022). "The reduction in bacterial loads in sublingually and intragastrically immunized IFN-γ-/- mice was associated with significantly higher levels of IL-17A in stomach extracts and lower gastritis scores compared with immunized wild-type mice." (PMID 26168305, 2015). "The reduction in the gastric bacterial loads of sublingually immunized IFN-γ-/- mice was associated with elevated IL-17A responses, and reduced post-immunization gastritis compared with sublingually immunized wild-type mice." (PMID 26168305, 2015). "Among the inflammatory cytokines evaluated in this study, IL-17A, IL-17F, and IL-22 can play a crucial role in developing gastritis, especially moderate gastritis, in infected patients with H. pylori." (PMID 39807418, 2024). "Upregulation of IL-17A positively correlated with the severity of gastritis has been reported in biopsies of H. pylori-infected individuals relative to uninfected controls." (PMID 36125689, 2023). "The main cytokines that induce inflammation in H. pylori-associated gastritis models are the Th1 cytokine interferon-g (IFN-g) and the Th17 cytokine interleukin-17A (IL-17A)." (PMID 34795977, 2021). "The aim of the current study was to define the function of IFN-γ and IL-17A in the vaccine-induced protection against H. pylori infection and post-immunization gastritis after SL immunization." (PMID 26168305, 2015). "Immunized IFN-γ-/- mice had a significantly elevated IL-17A secretion in the stomach, and lower gastritis scores compared with immunized wild-type mice." (PMID 26168305, 2015). "In summary, our results suggest that IFN-γ responses in the stomach of sublingually immunized mice promote vaccine-induced gastritis, after infection with H. pylori but that IL-17A primarily functions to reduce the bacterial load." (PMID 26168305, 2015). "We have investigated the function of IFN-γ and IL-17A for vaccine-induced protection and inflammation (gastritis) using IFN-γ-gene-knockout (IFN-γ-/-) mice, after sublingual or intragastric immunization with H. pylori lysate antigens and cholera toxin." (PMID 26168305, 2015). "Protection against H. pylori infection has been shown to be associated with post-immunization gastritis, and an increase in both IFN-γ and IL-17A in the stomachs of immunized mice." (PMID 26168305, 2015). "In summary, the elevated IL-17A responses in the stomach of sublingually immunized IFN-γ-/- mice had minor influence on the gastritis (atrophy and infiltration) scores compared to sublingually immunized wild-type mice." (PMID 26168305, 2015). "Additionally, an anti-inflammatory effect of IL-17A on H. pylori-induced gastritis through suppression of Th1 differentiation and bacterial colonization has been observed." (PMID 36125689, 2023). "Th17 cell-related pro-inflammatory cytokines (IL-17a and IL-17f) also contribute to gastritis, while Th1-independent gastritis could be ascribed to the hyper-activation of the Th17 cell subset." (PMID 32974219, 2020). "Since IL-22 works with IL-17A to stimulate the strongest antimicrobial response in gastric epithelial cells of humans and of mice, the importance of IL-22 alone was investigated in a mouse model of gastritis." (PMID 26867135, 2016). "The effect of IL-17A neutralization on the gastritis (atrophy and infiltration) in sublingually immunized IFN-γ-/- mice was also evaluated and found to be significantly lower than that in sublingually immunized IFN-γ-/- mice receiving the isotype control IgG antibody." (PMID 26168305, 2015).
gastritis (continued). "This study demonstrates that SA-derived extracellular vesicles (SA-EVs) accumulate in gastric tissue, enter epithelial cells, and induce acute gastritis characterized by neutrophil infiltration and elevated cytokines (TNF-α, IL-6, IL-17A)." (PMID 41614638, 2026). "The amounts of IL-2, IL-4, IL-17A, IL-17F, IL-22, TNF-α, and TFN-γ were significantly different in patients with gastritis compared with Hp- subjects." (PMID 39807418, 2024). "Accordingly, IL-2, IL-17-A, IL-17F, IL-22, TNF-α, and IFN-γ showed significant increases in patients with mild and moderate gastritis compared with the Hp- subjects." (PMID 39807418, 2024). "The levels of IL-2, IL-17A, IL-17F, IL-22, TNF-α, and IFN-γ were significantly higher in patients with mild and moderate gastritis than Hp- group (P≤0.05)." (PMID 39807418, 2024). "To correlate the local immune responses to the gastritis and protection in the vaccinated mice, we studied the gastric IFN-γ and IL-17A responses of IFN-γ-/- and wild-type mice." (PMID 26168305, 2015). "Remarkably, the neutralization of IL-17A in sublingually immunized IFN-γ-/- mice completely abolished protection against H. pylori infection and the mild gastritis." (PMID 26168305, 2015). "The aim of the current study was to determine whether protection could be separated from post-immunization gastritis after SL immunization by studying the role of IFN-γ and IL-17A in these two processes." (PMID 26168305, 2015). "Our results suggest that the post-immunization gastritis of sublingually immunized mice may be promoted by CD3+CD4- derived IFN-γ (and possibly other pro-inflammatory cytokines), whereas CD3+CD4+ derived IL-17A appears to be specific to the anti-bacterial response to H. pylori infection." (PMID 26168305, 2015). "Moreover, other inflammatory cytokines and chemokines (IL-27, IFN-β, IL-1α, IL-23, IL-22P70, TNF-α, IL-17A, IL-10, IL-1β, and MCP-1) were not showed dose-dependent changed in DFMO-treated mice compared to gastritis mice group." (PMID 32231118, 2020).
non-alcoholic fatty liver disease (34 papers, 2015 to 2025). "It decreased TNF-α, a key factor in Non Alcoholic Fatty Liver Disease (NAFLD) and Non Alcoholic Steato Hepatitis (NASH) development, as well as IL-6, IL-10, and IL-17A, which are implicated in obesity and NAFLD regulation." (PMID 38611444, 2024). "Liver MAIT cells from patients with cirrhosis (due to either alcoholic or nonalcoholic fatty liver disease) show alterations consistent with exhausted and pro-fibrotic activity, including increased frequencies of IL-17A+ cells." (PMID 35641678, 2022).